LOX (lysyl oxidase)
Diseases named in the same sentence as LOX in open-access papers (continued):
Sharing a sentence is not in itself a finding about the gene and the disease.
tumor (continued). "As such, whether LOX in the TME induces tumour progression or suppression still remains obscure." (PMID 35908277, 2022). "This structure provides non-specific resistance to proteolysis, thereby inhibiting tumor metastasis; however, in a hypoxic environment, high expression LOX creates an ECM that is excessively cross-linked and rigid, and this promotes tumor cell invasion and metastasis." (PMID 35956952, 2022). "Another possible reason may be that the LOX propeptide exerts a tumor suppressor effect." (PMID 36202905, 2022). "Thus, efficient inhibition of tumor progression may require the simultaneous inhibition of the activities of more than a single lysyl oxidase." (PMID 35682926, 2022). "Differences in LOX methylation levels in each group were studied according to histological type, gender, age, race, alcohol consumption frequencies, person cigarette smoking history pack-year, tumor stage, lymph node stage, metastasis stage, and disease-free status." (PMID 36090891, 2022). "LOX expression, responsible for the oxidative deamination of Lys residues in collagen precursors, collagen crosslinking and increased matrix stiffening, was correlated with increased tumor adhesion and migration, but also with possible roles in tumor suppression." (PMID 34566949, 2021). "Then, we studied whether LOX expressed by CAFs can significantly catalyze the cross-linking of collagen and increase matrix stiffness, thereby regulating the morphology and invasion of tumor cells in a FAK-dependent manner." (PMID 34930321, 2021). "In addition, it has been demonstrated that the tumor hypoxic microenvironment led to a high expression of lysyl oxidase (LOX) in CAFs with enhanced cross-linking enzymatic activity, creating the molecular tracks that pave the way for BC cells, to migrate beyond the primary tumor." (PMID 34885027, 2021). "To investigate whether pre-metastatic niche development could be driving the outgrowth of lung-disseminated tumor cells, we measured the expression of lysyl oxidase (LOX), a hypoxia-dependent tumor-secreted factor known to drive pre-metastatic niche development." (PMID 34556788, 2021). "However, the role of LOX in PCa remains unsettled and may have both tumor-suppressing and tumor-promoting effects." (PMID 35003355, 2021). "However, the relationship among CAFs, LOX, collagen and their mechanism in the remodeling matrix and influencing tumor progression in OSCC are still largely unknown." (PMID 34930321, 2021). "Thus, inhibiting LOX expression would appear to be a useful therapeutic tactic in tumor metastasis." (PMID 34815382, 2021). "LOX plays an important role in pre-metastatic niche formation by altering the extracellular matrix remodeling and thus its inhibition could prevent metastatic tumour growth." (PMID 35054220, 2021). "This leads to predominant degradation of loose collagen fibers and accumulation of highly crosslinked stiff collagen bundles during aging and in photodamaged skin which may contribute to enhanced tumor progression due to tissue stiffening, as has been reported for lysyl oxidase (LOX)." (PMID 34295891, 2021). "Therefore, it is reasonable to believe that LOX could promote tumor metastasis, angiogenesis, and proliferation in GC." (PMID 34583752, 2021). "In consistent with the reduction in tumor growth, there was also a significant reduction in the proliferation marker, Ki-67 and an increase in the expression of an apoptosis marker, Cleaved Caspase-3 in combination-treated group as compared to LOX inhibition or doxorubicin treatment alone." (PMID 32415208, 2020). "Interestingly, high LOX expression in the primary tumor is associated with bone metastases without affecting the primary tumor growth." (PMID 32232008, 2020).
tumor (continued). "The hub gene lysyl oxidase encodes an ECM protein that increases insoluble matrix deposition and tissue stiffness by crosslinking collagens with elastin, and is essential to enable tumor cells to escape from primary sites and grow at secondary sites during metastasis." (PMID 32477405, 2020). "Moreover, there was a correlation between LOX over expression and local tumor relapse." (PMID 32467737, 2020). "However, the LOX-mediated collagen cross-linking process activated by hypoxic tumor cells seems to favor stromal cells with respect to adhering and secreting more MMPs, further promoting the tumor invasion by degrading collagen." (PMID 30736469, 2019). "However, it should be noted, that this proangiogenic response was exerted by the LOX-induced production of VEGF by tumor cells and that whether this mechanism could operate in vascular endothelial cells in an autocrine manner was not evaluated." (PMID 31615160, 2019). "Furthermore, among the tumor cells we could observe cells with higher LOX expression level (moderate/strong IRS score) when compared to other cancer cells (mild/moderate IRS score) regardless the carcinoma type (red arrows)." (PMID 30583585, 2018). "Like LOX, also LOX-like proteins may function as tumor suppressors or promoters." (PMID 30701028, 2018). "Importantly, LOX as an important effector in tumor metastasis, may be a potential target for cancer therapy in the future." (PMID 29472856, 2018). "To evaluate the potential of lysyl oxidase inhibition to increase tumor supply and efficacy of drug delivery, we examined the effect of prolonged lysyl oxidase inhibition on several indicators for hypoxia, metabolic stress, and drug distribution in a range of tumor models." (PMID 29780168, 2018). "Previous studies have revealed several abnormally expressed genes in NPC that could serve as reliable prognostic factors, like H3K27me3, ULK1, LOX, Talin-1 and PTP4A3, however, the existing molecular markers are substantially limited in identifying tumor spread and aiding risk assessment." (PMID 29100406, 2017). "On the basis of our data, we propose a model whereby LOX activates the secreted protease HTRA1, which inhibits TGFβ1 signalling, causing increased expression of the EGF-like domain containing protein MATN2, which then enhances EGFR signalling to drive tumour growth and metastasis." (PMID 28416796, 2017). "In addition, we treated the AT-1 cells in vitro with increasing concentrations of recombinant LOX protein under both normoxia and hypoxia to determine whether LOX could affect tumour cell viability directly." (PMID 26804196, 2016). "However, other studies have suggested that the LOX enzymes suppress tumours." (PMID 26804196, 2016). "LOX promote tumour progression and metastasis, but it may also have tumour-inhibitory effects." (PMID 26804196, 2016). "By identifying the cooperative effect of these miRNAs in the regulation of LOX and examining their properties as biomarker, we were able to obtain a better insight into the role of miR-141-3p and miR-145-5p and their cooperation in tumor suppressive functions during tumorigenesis of ccRCCs." (PMID 27336447, 2016). "Therefore, the development of drugs targeting LOX may have therapeutic significance for the prevention and treatment of tumor metastasis." (PMID 28036074, 2016). "However, whether LOX enhances or suppresses tumor progression in various tissues, sites, sizes, and stages of tumors is still controversial." (PMID 28036074, 2016). "The reason to this is unknown but one possible explanation could be that increased LOX activity in the tumour-bearing organ, in contrast to the early tumour-promoting role in the tumour microenvironment, could be part of an insufficient defence trying to seal off the tumour." (PMID 26804196, 2016). "In addition, LOX expression may vary during the different stages of transformation as the molecular environment of the tumor changes in the different tissue types." (PMID 26882568, 2016).
tumor (continued). "Thus, LOX inhibition may also have impacts on tumor cells themselves that are mediated by integrin and fibronectin." (PMID 26077591, 2015). "Therefore, anticancer agents that concomitantly downregulate LOX might thereby also reduce tumor dissemination of sublethally treated tumor cells." (PMID 25052686, 2014). "The LOX concentrations that differed according to the type of tumor may also reflect that both re-modeled ECM (pre-cancerous niche - PCN) and normal-cell-to-cancer-cell transitions were encountered in different stages of completion, and thus the resulting expression levels were different." (PMID 24885752, 2014). "Finally, we compared LOX mRNA levels of primary tumours and lymph node metastases of 17 patients." (PMID 25141126, 2014). "Since LOX protein structure and function are so complex and involve vital biological processes, such as cell movement, signal transduction and gene regulation, it is evident that aberrant regulation of LOX may lead to tumorigenesis and tumor progression." (PMID 23425977, 2013). "Among the most strongly upregulated genes, we selected LOX for further investigation on the basis of published data, notably because its expression and activity are dependent on oxygen levels, and because it is known to have a role in tumor suppression, cell migration and invasion." (PMID 24265769, 2013). "The role of LOX in in cancer has been controversial, due to both down- and upregulation of LOX in tumor tissues and cancer cell lines, which have been found in initial studies, suggesting a dual role for LOX as a tumor suppressor, as well as a metastasis-promoting gene." (PMID 23425977, 2013). "In addition, TGF-β may also directly regulate ECM tension and stiffness (through increasing the expression of ECM proteins by tumor cells or CAFs and/or the function of LOX,) and thereby increasing the oncogenic activities (e.g. proliferation) of cancer cells." (PMID 21914164, 2011). "Given alone or with chemotherapy, a pan-LOX inhibitor, PXS-5505, modulated fibroblast and immune cell distribution and decreased tumor stiffness in the less-responsive mouse model." (PMID 41994332, 2026). "In this context, the functional synergy between LOX, PLOD2, and MMPs creates a microenvironment favorable for tumor invasion, where stiffness precedes localized enzymatic degradation of the extracellular matrix, facilitating cell migration and intravasation." (PMID 40906383, 2025). "LOX-driven ECM remodeling is also a potential therapeutic target, given its essential role in physically reshaping tissues to accommodate tumor growth." (PMID 40658744, 2025). "LOX and lysyl oxidase-like protein (LOXL), both copper-dependent enzymes, facilitate tumour invasion and metastasis in cancer by catalysing the cross-linking of extracellular matrix proteins and activating signaling pathways." (PMID 40433591, 2025). "GSVA results in our study showed that classical EMT pathways such as TGF‐β, Notch and WNT/β‐catenin were significantly enriched in LOX family high‐expressing tumours, which was highly consistent with previous finding that the TGF‐β/LOX/Snail axis drives EMT." (PMID 40179101, 2025). "As key players in shaping the biophysical properties of the tumor microenvironment, CAFs deposit abundant ECM fibers (including collagen) and crosslinking enzymes such as LOX, leading to increased matrix stiffness and fibrous reorganization." (PMID 40574854, 2025). "LOX has also been shown to interact with key signaling pathways like focal adhesion kinase (FAK) - YAP/TAZ, which are crucial for tumor cell survival and proliferation." (PMID 40661776, 2025). "LOX, responsible for collagen cross-linking and ECM stiffening, has been identified as a key driver of tumor invasiveness." (PMID 40149289, 2025). "Targeting matrix crosslinking, a key contributor to tissue stiffness, by inhibiting LOX or related LOXL family members in preclinical ovarian cancer models, has been shown to reduce tumour growth." (PMID 39917412, 2025).
tumor (continued). "Among the 7 HRGs included in the hypoxia risk score model constructed in this study, these 6 genes (LDHA, PGK1, PFKP, DCN, LOX, FBP1) have been extensively reported in previous studies for their roles in tumor hypoxia response and progression." (PMID 40464853, 2025). "CAF- and tumor-derived TGF-β induces LOX expression in CAFs, leading to collagen crosslinking and a rigid ECM that paradoxically supports tumor cell migration and formation of PMN." (PMID 41409250, 2025). "In addition, the Radiomics_score of the LOX high‐expression group was significantly higher than the low‐expression group in both of the radiomic models, with a p value of 0.0062 in the radiomic model of whole‐tumor and 0.0062 in the radiomic model of whole‐tumor and peri‐tumor." (PMID 40792413, 2025). "In fibroblasts, ECM regulators such as LOX and MMP11 reinforce tumor-supportive stroma and impede immune infiltration." (PMID 41164190, 2025). "In colorectal cancer (CRC), LOX enhances tissue stiffness and triggers the FAK/Src signaling cascade, accelerating tumor progression." (PMID 40721833, 2025). "Matrix remodeling enzymes, such as MMPs and lysyl oxidase (LOX), alter ECM integrity and stiffness, enhancing tumor cell motility and invasiveness." (PMID 40227764, 2025). "LOX also has a critical role in endothelial cell (EC) proliferation and contributes to angiogenesis in HCC via VEGF expression, which can be induced by tumor initiating cell (TIC) enrichment." (PMID 40792413, 2025). "This study highlights the prognostic significance of HIF-1α, LOX and ITGA5 expression in the tumor microenvironment, particularly in the context of KRAS/NRAS/BRAF mutation status." (PMID 39857068, 2025). "RT-qPCR and WB techniques were used to detect the expression of LOX, LOXL1, LOXL2, LOXL3, and LOXL4 in tumor tissues." (PMID 40270974, 2025). "The lysyl oxidase (LOX) family stabilizes collagen and elastic fibers, regulating EMT and tumor progression." (PMID 40370437, 2025). "In addition, the Radiomics_score of the LOX high‐expression group exhibited a significant increase compared to the low‐expression group in both radiomic models, with a p value of 0.0062 in the radiomic model of the whole‐tumor and 0.0062 in the radiomic model of the whole‐tumor and peri‐tumor." (PMID 40792413, 2025). "The aim of this study is to investigate the interactions of the molecules HIF-1α, LOX and ITGA 5 key players in tumor microenvironment and ECM remodeling—whose roles and interplay in drug resistance have been previously reported in preclinical studies." (PMID 39857068, 2025). "Future approaches that combine immune modulation with matrix-targeting strategies—such as LOX inhibitors, integrin blockers, or MMP antagonists—hold promise for disrupting tumor–stroma interactions and improving patient outcomes." (PMID 40725175, 2025). "The main cellular compartment responsible for ECM remodeling are fibroblasts that are activated by the primary tumor secretome, and secrete both ECM proteins and regulators, such as LOX or MMPs." (PMID 40370456, 2025). "Ultimately, akin to BAPN or LOX gene ablation, CCT365623 downregulates MATN2, impeding EGFR plasma membrane localization in tumors and inhibiting tumor growth and metastasis in mice." (PMID 39979279, 2025). "Chelation with Zn activates the cGAS-STING pathway to induce tumour cell death.D-pen binds to Cu generate ROS and inhibit ICAM and LOX." (PMID 40809021, 2025). "The results revealed that high PFKFB3 expression was positively correlated with larger tumour size, as well as increased expression of COL1, LOX and the COL1High/LOXHigh signature." (PMID 41292194, 2025). "LOX catalyzes the cross-linking of elastin and collagen in the extracellular matrix (ECM) and promotes the formation of tumor cell migration and metastasis." (PMID 40396123, 2025). "Inhibitors of LOX, such as PXS‐5505, have demonstrated preclinical efficacy in reducing ECM stiffness and inhibiting tumor progression, particularly in pancreatic cancer." (PMID 40686923, 2025).
tumor (continued). "On the other hand, increased activity of lysyl oxidase enzymes leads to collagen crosslinking and subsequent stiffening of the ECM, which are major drivers of fibrosis, tumor progression, and metastasis." (PMID 40170697, 2025). "Our study comprehensively examined the hypoxia pathway in the tumor microenvironment, focusing on the expression of HIF-1α, LOX and ITGA5 and their prognostic implications." (PMID 39857068, 2025). "The LOX inhibitor β-aminopropionitrile (BAPN) suppresses LOX enzymatic activity, blocks collagen crosslinking, reverses tumor ECM stiffness, and reduces collagen fiber thickness, linearization, and density." (PMID 40574854, 2025). "This led to the development of PXS-5505, a first in-class selective pan-LOX inhibitor which inhibits ECM stiffness, CAF activation and tumour metastasis." (PMID 38514607, 2024). "Studies have shown that inhibiting the activity of lysyl oxidase (LOX) can improve the structure of ECM, significantly reduce the degree of ECM fibrosis, and has great potential for tumor therapy." (PMID 39682291, 2024). "Lysyl oxidase enzymes (LOXs), as extracellular matrix (ECM) protein regulators, play vital roles in tumor progression by remodeling the tumor microenvironment." (PMID 38978755, 2024). "Regarding gene expression, they reported higher expression of lysyl oxidase in hard tumors with FDR-adjusted p = 0.0279, suggesting that the extracellular matrix plays a vital role in the etiology of tumor stiffness." (PMID 38392013, 2024). "It was demonstrated that LOX and LOXL2 overexpression hampers doxorubicin diffusion in tumor spheroids, but this effect was reversed by inhibiting lysyl oxidase with 2-aminopropionitrile." (PMID 39594723, 2024). "Interfering with these interactions by inhibiting LOX signals can reduce TAM invasion and inhibit tumor growth." (PMID 39206155, 2024). "The involvement of LOX in PMN formation has been demonstrated, particularly after early-stage tumor resection, even before detectable metastases emerge." (PMID 38231464, 2024). "Collagen restructuring occurs primarily because of the increased activity and expression of a range of enzymes (including lysyl oxidase (LOX), transglutaminase (TGase), and matrix metalloproteinase (MMP)) within the dynamic tumor matrix." (PMID 39421736, 2024). "Taken together, these data strongly suggest that pan-LOX inhibition with PXS-5505 promotes more efficient chemotherapy penetration, resulting in decreased tumor burden." (PMID 39101793, 2024). "Thomas Cox (Garvan Institute, Australia) discussed the discovery of small molecules targeting lysyl oxidase (LOX), which is essential for collagen deposition, ECM integrity and tumour desmoplasia." (PMID 38514607, 2024). "Lysyl oxidase (LOX) is an enzyme that modulates the primary tumor microenvironment by stiffening the ECM and boosting the tumor’s ability to invade and metastasize." (PMID 38339384, 2024). "For example, increased ECM stiffness, as seen with lysyl oxidase (LOX) overexpression, promotes cellular proliferation and survival through mechanisms like focal adhesion kinase (FAK) activation, while also enhancing tumor invasiveness." (PMID 37895855, 2023). "Combination of anti-PD-1 and LOX inhibition resulted in an increased accumulation of effector CD8+ T cells in the tumor and significant delays on tumor progression in a pancreatic cancer mouse model." (PMID 37284199, 2023). "In cancer cell lines, LOX activity is inhibited by silencing the ATP7A gene, which reduces tumour growth and metastatic potential." (PMID 37049685, 2023). "When LOX is active, it stimulates transcription via Twist to promote EMT in the tumor environment, and increased expression of LOXL2 correlates with metastasis and poor survival in breast cancer patients." (PMID 38139406, 2023).